Y_RNA (Y RNA )
Gene: Miscellaneous RNA gene on chromosome 4 (5,426,885 to 5,426,984, reverse strand). Ensembl gene ENSG00000252266.
Homologues: Orthologues: chimpanzee Y_RNA (96% identical), macaque Y_RNA (93% identical). Paralogues in human: Y_RNA (81% identical), Y_RNA (80% identical), RNY3P1 (79% identical), Y_RNA (79% identical), RNY3 (78% identical), Y_RNA (78% identical), Y_RNA (77% identical), Y_RNA (76% identical), RNY3P16 (75% identical), RNY3P2 (75% identical), RNY3P3 (75% identical), Y_RNA (75% identical), and 90 more.